RB1 (RB transcriptional corepressor 1)
Diseases named in the same sentence as RB1 in open-access papers (continued):
Sharing a sentence is not in itself a finding about the gene and the disease.
retinoblastoma (continued). "All RB1-/- cell lines, in addition to two out of the 4 primary RB1-/- retinoblastomas (RB 2133 and RB 2362) demonstrated higher miR-24 expression than the RB1+/+ cell lines." (PMID 22336108, 2012). "We demonstrate that most human retinoblastomas in which RB1 is inactivated (RB1-/-) show low ARF protein despite high ARF mRNA." (PMID 22336108, 2012). "To identify the spectrum and the effect of germline mutations and to provide accurate genetic counseling, we performed a genetic analysis of the RB1 gene in a Moroccan retinoblastoma cohort." (PMID 22219649, 2011). "It was first discovered, with further chimera experiments, that p107 ablation with Rb1 ablation efficiently produces retinoblastomas and early mortality in mice." (PMID 21403899, 2011). "In conclusion, in spite of the technical difficulty of analysis, screening for the RB1 gene remains an integral component of managing patients with retinoblastoma." (PMID 22219649, 2011). "Deregulation of RB1 has been reported in multiple types of tumors, including retinoblastoma, cervical cancer, and SCLC." (PMID 21447152, 2011). "The retinoblastoma gene (RB1) is a tumor suppressor gene that was first discovered in a rare ocular pediatric tumor called retinoblastoma (RB)." (PMID 20664703, 2010). "For the RB1 5′ UTR, the Retinoblastoma associated SNPs collapse the structural ensemble from three clusters to one." (PMID 20808897, 2010). "In some cases of retinoblastoma, RB1 was epigenetically silenced by hypermethylation at the promoter region, resulting in reduced RB1 expression." (PMID 19640284, 2009). "Structural alterations of RB1 seem to be involved in the pathogenesis of the secondary malignancy after treatment of retinoblastoma." (PMID 19077296, 2008). "As in retinoblastoma, it is clear that a combination of techniques will need to be applied in order to identify the precise mechanisms of RB1 inactivation in breast cancer." (PMID 18782450, 2008). "Some of them are reported to share the same oncogenes, as WT1 in Wilms' tumour, in retinoblastoma and in acute myeloid leukaemia, and RB1 in retinoblastoma, neuroblastoma, childhood leukaemia and Ewing's sarcoma." (PMID 17595660, 2007). "The RB1 gene was the first tumor suppressor gene cloned from humans by studying genetic lesions in families with retinoblastoma." (PMID 16672052, 2006). "Inheritance of germline RB1 mutation causes retinoblastoma with 90% penetrance in children; the tumor cells exhibit loss of heterozygosity (LOH) at the RB1 locus with the invariable loss the normal RB1 allele." (PMID 17183714, 2006). "Despite the identification of the RB1 gene and the current insight into the function of pRB, the understanding of the sequence that leads to human retinoblastoma is still incomplete." (PMID 16934146, 2006). "His colleagues studied the genetic lesions in children with heritable retinoblastoma and cloned the first human tumor-suppressor gene RB1, supporting Knudson's two-hit model." (PMID 16231976, 2005). "For the very small group of parents known to be carrying a germline RB1 mutation but not affected by retinoblastoma, there was a lower and non-significant increase in risk (SIR = 1.9)." (PMID 42122192, 2026). "Furthermore, MYCN overexpression profoundly perturbs critical molecular pathways and the retinal cellular microenvironment, promoting tumor initiation and progression—particularly in RB1-proficient retinoblastoma." (PMID 40943594, 2025). "The tumor suppressor gene RB1 was initially discovered in retinoblastoma." (PMID 40296890, 2025). "We further found that cone precursors highly express SYK, an oncoprotein previously detected in human retinoblastomas and RB1-null retinal organoids but not in healthy tumor-associated retina." (PMID 40767624, 2025). "Genetic testing is ideally indicated in all children diagnosed with retinoblastoma with an unknown RB1 status." (PMID 41009976, 2025).
retinoblastoma (continued). "The relationship between BRAF mutations and RB in retinoblastoma is not as well documented as other genetic alterations like RB1 mutations or MYCN amplification." (PMID 40317918, 2025). "MYCN amplification without concurrent RB1 mutations characterizes a rare yet highly aggressive subtype of retinoblastoma; however, its precise developmental origins and therapeutic vulnerabilities remain incompletely understood." (PMID 40943594, 2025). "The results obtained are an approach to the study of genetic variants in patients with retinoblastoma, since the database analyzed is not a complete list of variants that occurred in the RB1 gene." (PMID 41301786, 2025). "Non-heritable retinoblastoma, which accounts for about 60% of cases, arises when both RB1 mutations occur somatically in a single retinal progenitor cell, typically resulting in unifocal, unilateral disease." (PMID 41002743, 2025). "Therefore, in the presence of a partially functional RB1 protein, the precursor cells form a retinocytoma instead of a retinoblastoma." (PMID 40001157, 2025). "In rare cases, it could also be due to retinoblastoma with MYCN amplification with wild-type RB1 (MYCNARB1+/+)." (PMID 40338593, 2025). "Although the functional relevance of these non-RB1 loci to retinoblastoma remains largely uncertain, their annotation in ClinVar highlights the possibility that broader genomic contexts may occasionally be implicated." (PMID 41150792, 2025). "OS risk is elevated in individuals who have retinoblastoma predisposition RB1; the RB1 protein is a negative cell cycle regulator." (PMID 39941818, 2025). "The RB1 gene is the central driver of retinoblastoma and the most established gene." (PMID 41009976, 2025). "In such cases, individuals with two normal copies of RB1 never develop retinoblastoma unless both alleles undergo somatic mutation in a retinal cell." (PMID 41002743, 2025). "By integrating next‐generation sequencing and comprehensive genetic analyses, which revealed no germline RB1 or other hereditary cancer syndrome mutations, we confirmed the nonhereditary nature of the patient's retinoblastoma." (PMID 41307228, 2025). "Retinoblastoma (RB), the most common intraocular cancer in children, arises from retinal progenitor cells that carry biallelic RB1 inactivation and is characterized by rapid proliferation, poorly differentiated histology, and a propensity for extraocular spread if left untreated." (PMID 41374987, 2025). "The mean age at diagnosis for patients with bilateral retinoblastoma, differentiated by the presence or absence of germline RB1 mutations, was observed to be 22.9 months (±13.1 months) and 24.3 months (±19.2 months), respectively." (PMID 40317918, 2025). "The detection of somatic RB1 pathogenic variation is critical for confirming a diagnosis of non-heritable retinoblastoma." (PMID 38672657, 2024). "Moreover, lentivirus-mediated over-expression of MYCN in human RB1-proficient foetal retina also induces tumorigenic growth resembling retinoblastoma." (PMID 37606819, 2024). "Hereditary retinoblastoma—RB1, a tumor suppressor gene, is the first gene linked to a childhood CPS, and those carrying a pathogenic variant in this gene go with a primarily increased risk for retinoblastoma." (PMID 38893137, 2024). "Contrary to human cases where MYCN amplification drives retinoblastoma without RB1 mutation, in a mouse model, overexpressing MYCN in retinal cells with wildtype pRB did not induce tumor formation." (PMID 39000021, 2024).
retinoblastoma (continued). "As illustrated for patients with retinoblastoma and no RB1 germline variants, tumor sequencing data can also be used to refine surveillance recommendations for siblings and future children." (PMID 38803632, 2024). "Furthermore, aside from presenting low levels of RB1 expression, retinoblastoma cells show low levels of the mRNAs for the RB1 paralog RBL2, suggesting that the G1/S restriction point is severely impaired." (PMID 38332874, 2024). "Such retinoblastomas are formed and diagnosed earlier, have faster and more aggressive growth, are less differentiated and more prone for metastasis than RB1-deficient retinoblastomas without MYCNA." (PMID 37606819, 2024). "LOH or RB1 mutations are linked to the lack of expression of this gene in retinoblastoma and other malignancies, such as bladder carcinomas and malignant neuroendocrine lung carcinomas." (PMID 39132504, 2024). "While patient 4 was affected by sporadic retinoblastoma without germ line alteration of RB1, the others harbored a heterozygous pathogenic variant in the RB1 gene in constitutional DNA." (PMID 38240863, 2024). "Prior investigation suggested that retinoblastoma arises from primitive retinal stem cells or cone photoreceptor cells of the retina, which exhibit a tendency towards depletion of the Retinoblastoma 1 (RB1) gene." (PMID 38540335, 2024). "The “two‐hit” hypothesis was initially proposed by Alfred Knudson in 1971 in the context of tumor suppressor genes explaining the retinoblastoma development by the appearance of two events affecting the tumor suppressor gene RB1 (Knudson Jr., 1971)." (PMID 39137949, 2024). "For example, the rare and aggressive MYCN-amplified RB1-wildtype subtype retinoblastoma is more therapy resistant to traditional chemotherapies, but equally chemo-sensitive to pevonedistat (a neddylation inhibitor), which is being developed as treatment for neuroblastoma." (PMID 37615761, 2024). "RB1-proficient MYCNA retinoblastoma could potentially arise from a different cell of origin or at a different maturation stage than RB1−/− retinoblastomas." (PMID 39079981, 2024). "In conclusion, this study found that 28% of patients with unilateral Rb (23% of those with a negative family history of Rb) had germline RB1 mutations." (PMID 39234041, 2024). "98% of non-hereditary retinoblastoma result from somatic loss of both RB1 alleles in a retinal precursor cell." (PMID 37658463, 2023). "In retinoblastoma, the presence of wild-type RB1 is unexpectedly observed in 2.7% of cases." (PMID 36982482, 2023). "Indeed, MYCN amplification has been found as a significant prognostic marker in a small sub-cohort of retinoblastomas carrying functional wt copies of the RB1 gene." (PMID 36982482, 2023). "Notably, half of the RB1 wild-type retinoblastoma cases analyzed in this study were characterized by MYCN amplification which was instead absent in most RB1 mutated tumors (97.3%)." (PMID 36982482, 2023). "Retinoblastoma is one of the first tumors that demonstrated the tumor suppressor role of RB1 gene." (PMID 37658463, 2023). "Retinoblastoma (RB1) was one of the first tumor suppressors to be identified." (PMID 38577257, 2023). "The RB1 sequencing method would not detect 100% of retinoblastomas, because around 1% do not harbor RB1 mutations." (PMID 36148636, 2023). "According to Knudson's “two-hit” hypothesis, both copies deletion of RB1 are critical for retinoblastoma formation." (PMID 36714839, 2022). "Four retinoblastoma tumors displayed RB1–/+ status and 7 exhibited RB1+/+ genotypes." (PMID 36245757, 2022). "Although we have focused on intraocular advanced and non-advanced retinoblastoma tumors, our findings can be extended to other cancer systems with persistent RB1 mutations." (PMID 35626705, 2022).
retinoblastoma (continued). "Retinoblastoma classically arises due to mutations in both alleles of the retinoblastoma susceptibility gene (RB1), resulting in a lack of regulation at the G1-S checkpoint of the cell cycle and subsequent unchecked cellular proliferation." (PMID 36553382, 2022). "Atypical RB1 germline variants have been described in sarcoma patients without retinoblastoma as a primary tumor." (PMID 36497448, 2022). "Since genetic inactivation is required in both copies of RB1 to induce retinoblastoma, it has been proposed that prenatal exposure to pesticides could act as a second hit." (PMID 35563062, 2022). "Inactivation and loss of RB1 results in overexpression of HELLS and increased proliferation of retinoblastoma tumors; HELLS has therefore emerged as a potential new therapeutic target for retinoblastoma." (PMID 36012581, 2022). "Most retinoblastomas are genetically characterized by biallelic inactivation of the RB1 gene." (PMID 36245757, 2022). "This study aimed to establish whether the high-level MYCN-amplified, RB1-proficient (MYCNARB1PRO) retinoblastoma present in this cohort displays unique molecular features that discriminate them from the rest of the retinoblastoma genomic subtypes." (PMID 36245757, 2022). "The upregulation of translation and mRNA synthesis in MYCN-amplified RB1-proficient retinoblastomas may be the direct outcome of MYCN overexpression." (PMID 36245757, 2022). "This in turn may point to differential biological or oncogenic dynamics within this rare retinoblastoma subtype, which is already clinically reflected in the earlier age at diagnosis compared with that of classical RB1–/– retinoblastomas." (PMID 36245757, 2022). "However, studies of hereditary retinoblastoma tumors brought about the discovery of Rb1 as a prototype tumor suppressor gene whose homozygous inactivation leads to the development of tumors." (PMID 35267571, 2022). "The fact that we find downregulation of genes that are important for proliferation in MYCN-amplified RB1-proficient retinoblastoma may initially seem counterintuitive." (PMID 36245757, 2022). "In addition, cilia assembly was also identified as a potential differential regulated pathway in MYCN-amplified RB1-proficient retinoblastomas compared with the rest of the cohort." (PMID 36245757, 2022). "We did not detect an RB1 germline mutation in our retinoblastoma patient, however, the mutational status of the tumor is not known." (PMID 35221838, 2022). "Forty-seven retinoblastoma tumors, comprising 36 RB1–/–, 4 RB1+/–, and 7 RB1+/+ tumors." (PMID 36245757, 2022). "Non-heritable retinoblastoma is characterized by inactivation of both alleles of the retinoblastoma gene (RB1, on chromosome 13q14)." (PMID 36497295, 2022). "Interestingly, the two MYCN-amplified retinoblastomas that were included in this cohort clustered together with the undifferentiated RB1–/– retinoblastomas." (PMID 36245757, 2022). "We also wanted to determine whether MYCN over-expression can generate retinoblastoma with high frequency in RB1-proficient retina." (PMID 35729105, 2022). "The MYCN amplification status was analyzed, because it was published that in a subgroup of retinoblastoma, no RB1 mutation was found, but instead a MYCN amplification." (PMID 36497295, 2022). "The finding that Rb1 loss is not sufficient for retinoblastoma in mice is unexpected but has inspired more careful analysis to uncover possible explanations." (PMID 35368709, 2022). "In addition, their histologic appearance differs from the classic RB1–/– retinoblastoma, showing an undifferentiated phenotype." (PMID 36245757, 2022).
retinoblastoma (continued). "The Rb1 locus is located on the q arm of chromosome 13, and the presence of genetic rearrangements in this region in retinoblastoma tumors was one of the crucial pieces of evidence for the identification of Rb1 as a key player in the development of such tumors." (PMID 35267571, 2022). "The majority of patients with sporadic unilateral retinoblastoma has non-heritable retinoblastoma, but only molecular genetic analysis can identify the minority among these that carry a constitutional RB1 variant and heritable retinoblastoma." (PMID 33919815, 2021). "Retinoblastoma is usually initiated by biallelic inactivation of the RB1 tumor suppressor gene." (PMID 34552068, 2021). "Interestingly, previous research has sequenced flanking deletion breakpoints in the RB1 gene in retinoblastoma tumors and found 4 to 7 bp direct repeat deletions." (PMID 34639028, 2021). "In a group of 316 sporadic retinoblastoma patients without a family history (223 patients with unilateral form of the disease and 93 with bilateral form) mutations in the RB1 gene in peripheral blood DNA were detected in 55% (175/316) of cases." (PMID 34680218, 2021). "It has been hypothesized that some genes deleted together with RB1 would be necessary for retinoblastoma development." (PMID 34479642, 2021). "Because of the fact that 98% of retinoblastoma cases begin after a double RB1 hit, according to Knudson’s hypothesis, all these children are at a major risk of being affected." (PMID 34479642, 2021). "Identification of RB1 mutations in retinoblastoma patients is possible in about 95% of cases, irrespective of clinical form of the disease and family history, only if the tumor material is available for molecular genetic testing." (PMID 34680218, 2021). "Although MYCN amplification in association with RB1 inactivation is known to occur, approximately 2% of retinoblastoma tumors have no derangement in RB1, and reportedly exhibit only MYCN amplification." (PMID 33466343, 2021). "We used whole-genome sequencing to investigate the landscape of mutations in a cohort of sporadic retinoblastomas, including cases where mutations in both copies of RB1 had not been previously identified." (PMID 33670346, 2021). "A second RB1 hit is present exclusively in the retinoblastoma sample (RB1 c.958C>T p.Arg320Ter)." (PMID 34479642, 2021). "Retinoblastoma RB1-deficient cells were not able to survive in the absence of MED4 in vitro and in a xenograft mouse model in vivo." (PMID 33591981, 2021). "Indicating either a deficiency in testing sensitivity or strategy, or alternatively, 6p gain may represent an independent biomarker for retinoblastoma in the presence of wildtype RB1." (PMID 33466343, 2021). "In contrast, none of 3 cases in non–RB1-associated tumor types had second hits (although the RB1 GPVs likely played a role in the preceding bilateral retinoblastomas that were not tested)." (PMID 34792595, 2021). "Retinoblastoma is thought to result from the inactivation of the RB1 gene." (PMID 34815392, 2021). "Depletion of RB1 within the different RPCs indicated post-mitotic cone-precursors to be most prone to develop into retinoblastoma, based on its ability to form tumors with expression of retinoblastoma markers upon xenografting in mice." (PMID 33718380, 2021). "Among patients with identified RB1 mutations but without clinical family history of retinoblastoma, 7% (12/175) were found to have hereditary disease with one of the parents being an asymptomatic carrier of an RB1 mutation." (PMID 34680218, 2021). "However, in contrast to human, mouse retinal cells were proven insensitive to Rb1 depletion and required additional knock-outs of tumor suppressors p107 or p130 for retinoblastoma development." (PMID 33718380, 2021). "In addition, the use of WBC sequencing revealed the germline origin of observed copy number deletions in ATM, BRCA2, and for two patients with retinoblastoma, RB1, based on deletions in their matched WBC sample." (PMID 34145282, 2021).